MIR1827 (microRNA 1827)
Synonyms: hsa-mir-1827; MIRN1827
Gene: MicroRNA gene on chromosome 12 (100,189,884 to 100,189,949, forward strand). Ensembl gene ENSG00000221476.
Gene Ontology:
Biological process: miRNA-mediated post-transcriptional gene silencing
Cellular component: RISC complex